RN7SL341P (RNA, 7SL, cytoplasmic 341, pseudogene)
Gene: Miscellaneous RNA gene on chromosome 2 (64,817,378 to 64,817,675, forward strand). Ensembl gene ENSG00000275588.
Homologues: Orthologues: chimpanzee Metazoa_SRP (99% identical), macaque Metazoa_SRP (94% identical). Paralogues in human: RN7SL1 (83% identical), RN7SL2 (83% identical), RN7SL126P (82% identical), RN7SL3 (82% identical), RN7SL408P (81% identical), RN7SL679P (81% identical), RN7SL650P (80% identical), RN7SL664P (80% identical), RN7SL88P (80% identical), RN7SL91P (80% identical), Metazoa_SRP (80% identical), RN7SL451P (80% identical), and 703 more.